PRKCA (protein kinase C alpha)
Diseases named in the same sentence as PRKCA in open-access papers (continued):
Sharing a sentence is not in itself a finding about the gene and the disease.
cancer (continued). "Importantly, we have demonstrated that PLCE1 and PRKCA are slightly expressed in normal esophageal epithelial cells, and that their expression levels are gradually increased during esophageal inflammation, progression, and malignant transformation – cancer-in-situ and invasive ESCC." (PMID 28402280, 2017). "Cancer-related genes with significant up-regulation in all ATCs included MYC, mTOR, PRKCA and TGFB1." (PMID 26680454, 2015). "Second, our pipeline was able to recapitulate most known translocation events in cancer (ALK, BRAF, EGFR, FGFR1, 2 and 3, NTRK1, 2 and 3, PDGFRA, PRKCA, RAF1, RET, ROS1)." (PMID 25204415, 2014). "CDK5R2, NEK9, PRKCA, PXK and STK11 have significant effects on growth of cancer cells in all cancer cell lines." (PMID 22761558, 2012). "The network with the highest significance also contained several cancer-related genes with high expression levels, including DSG2, PRKCA, PLA2G10, and Grp94." (PMID 17726464, 2007). "PTS treatment facilitates DNMT3B recruitment to regions with diminished OCT1 binding, resulting in hypermethylation of the protein kinase C alpha (PRKCA) promoter and the DNA-damage-inducible transcript 2 (DANT2) and troponin T2 (TNNT2) enhancers, thereby inhibiting cancer cell growth." (PMID 41226811, 2025). "Sinapic acid is a potent anti-oxidant used for the treatment of cancer, infections, oxidative stress, and inflammation; its anti-cancer mechanism works through the regulation of multiple proteins (CTNNB1, PRKCA, CASP8, SIRT1) and cytochrome enzymes (CYP1A1, CYP3A4)." (PMID 38999065, 2024). "On the other hand, the averaged copy number of PRKCA in MCF-10A is higher than that in the other three cell lines, indicating the potential negative effect of PRKCA in cancer cells." (PMID 36478047, 2023). "Some circRNAs implicated in oxidative stress and inflammation-related disorders are circ-PRKCA, circ-ZNF83, circ-PLEKHM3, circ-FNDC3B, circ-102115 circSATB2 and circFOXM1 on which natural products modulation have been investigated in cancers and other disorders." (PMID 37168992, 2023). "Other ncRNAs involved in oxidative stress and inflammation-related disorders are circular RNAs such as circ-PRKCA, circ-ZNF83, circ-PLEKHM3, circ-FNDC3B, circ-102115 circSATB2 and circFOXM1 on which natural products modulation have been investigated on in cancers and other chronic diseases." (PMID 37168992, 2023). "Curcumin decreases circ-PRKCA, a sponge for miR-384, resulting in miR-384 increase and ITGB1 decrease, which, all together, leads to a decrease of the biological aggressiveness of cancer cells." (PMID 37376060, 2023). "Interestingly, we found 23 genes whose expression were significantly altered by SV (P<0.05, unpaired t-test) and among them were well-known cancer-related genes CDKN2A (SV in 5 samples), PRKCA (SV in 3 samples) and EP300 (SV in 3 samples)." (PMID 28548104, 2017). "Those pathways specifically altered in primary tumors were associated with an abnormally increased expression of genes that are involved in focal adhesion (e.g., PRKCA, CRK, and BCL2), PI3K-Akt signaling (e.g., PHLPP2, PRKCA, PPP2R3A and KIT) and cancer pathways (e.g., COL4A5, LAMC1 and BCL2L1)." (PMID 27662660, 2016). "It seems that HDAC6, protein kinase C alpha (PKCα), and beta-catenin are all involved in the induction of type I interferon (IFN) transcription that occurs when the cell becomes infected with a cancer virus." (PMID 23644884, 2013). "Moreover, lowering PRKCA (protein kinase C alpha) and PTK6 (protein tyrosine kinase 6) could also inhibit cell growth, proliferation, and cancer progression." (PMID 37834191, 2023). "Also, we predicted that PRKCA, PRKCD, and PRKCE might be involved in improving the response of many cancers to PD-L1 blocking-dependent immunotherapies, but their effect on HLA-dependent therapies may run in line with their effect on the TILs aggregation." (PMID 35174160, 2021).
cancer (continued). "FYN (0.95% of cases) and PRKCA (1.58% of cases) have not been listed as driving genes by CGC, but studies have found that they are associated with many cancers and overexpressed in cancer patients." (PMID 34560840, 2021). "For the positive–negative subjects (screening), 3 CNAs were detected in BC genes (ACVR2A, CUL3 and PIK3R1), and 5 SNPs were identified in 6 non-BC cancer genes (SNIP1, TBC1D10B, PANK1, PRKCA and RUNX2; SUPT3H)." (PMID 35589867, 2022).
tumor (179 papers, 2003 to 2026). "NRAS (n = 3) and NF1 co-mutations (n = 2) were identified in PRKCA fusion-positive tumors, and one tumor harbored a PRKCA fusion with NF1." (PMID 35326655, 2022). "Consistent with upregulation of the wild-type alleles, increased PRKCA expression was reported in the tumor in which the fusion was originally detected." (PMID 33617877, 2021). "In the Vienna cohort, reduced OS and DFS and tumor recurrence at the last follow-up were significantly associated with PRKCA upregulation in the total cohort and the young patient fraction (all univariate p ≤ 0.002)." (PMID 33923093, 2021). "PRKCA has also been reported to be a dominant tumor progression factor that is associated with tumor proliferation and survival." (PMID 30651137, 2019). "In each tumor, a G>C transversion mutation in the PRKCA gene was identified causing a c.1387G>C, p.D463H substitution (reference transcript NM_002737)." (PMID 29476136, 2018). "The cases with the highest PRKCA mutant allele frequencies had genomic DNA that was isolated from areas histologically visualized to contain a high tumor cell content." (PMID 29476136, 2018). "Nonetheless, among MCs we identified one tumor harboring a GNAQ p.Q209L mutation and one case with an ATP2B4/PRKCA fusion." (PMID 41324772, 2025). "Among the most enhanced kinases was PRKCA, which regulates cell growth and survival, acting as both tumor suppressor and promoter depending on the physiological context." (PMID 39833546, 2025). "The carboxyl-modified PEI was used as a gene carrier in response to tumor-specific activation of protein kinase C alpha (PKCα) to release plasmid DNA (pDNA) for gene expression." (PMID 36662059, 2022). "PICK1 (Protein Interacting With PRKCA 1) codes for a protein which interacts with protein kinase C alpha (PRKCA), and it has been identified as a tumour suppressor gene in astrocytic tumours." (PMID 35774118, 2022). "BRAF V600E mutations were linked to GG with CD34 expression, FGFR1 mutations to DNT, MYB alterations to AG and also IDG and PRKCA fusions to PGNT, suggesting the possibility to also develop a genetically driven tumor classification scheme for LEAT." (PMID 32151273, 2020). "Pharmacological inhibition of PRKCA can reduce the growth and survival of tumors, promote apoptosis, and sensitize tumor cells to chemotherapy." (PMID 30651137, 2019). "CCN1 inhibits the microRNA miR-126, a potent VEGF inhibitor, inhibitor of angiogenesis, and tumour suppressor, via the protein kinase C-alpha (PKC-α) signaling pathway." (PMID 29996499, 2018). "In addition, it has been described that the kinase PRKCA/PKCα, which regulates hypoxia-induced autophagy, also promotes tumor-initiating cells (TICs) renewal, driving CRC initiation and progression." (PMID 40917756, 2025). "Also, the kinase PRKCA/PKCα regulates hypoxia-induced autophagy and promotes tumor-initiating cells (TICs) renewal, thus driving CRC initiation and progression." (PMID 40917756, 2025). "Also, we studied the relationship of tumor mutational burden (TMB) with survival in TC patients with low and high PRKCA expression." (PMID 39596225, 2024). "This is explained by PHF8 interaction with c-Jun and removal of H3K9me2 methylation to activate PRKCA (coding PKCα) and promote SRC-induced degradation of PTEN, a tumor suppressor commonly mutated in tumors and whose dysfunction is key to activate PI3K–AKT signaling." (PMID 39311138, 2024). "It inhibits tumor growth mainly by inhibiting PRKCA/SPHK/S1P signaling and antiapoptotic signaling." (PMID 35965565, 2022). "The role of PRKCA as a tumorigenic marker is plausible: Protein kinase C isoforms have been long identified as the intracellular receptors of phorbol esters that promote tumor formation during two-stage chemical-induced carcinogenesis in mouse skin." (PMID 33923093, 2021). "Additionally, Western blotting indicated that PRKCA and p-p38 protein levels in tumor tissues were significantly reduced in mice treated with hsa_circ_0007580 shRNA." (PMID 32681720, 2020).
tumor (continued). "PRKCA knock-out is sufficient to induce tumor formation in the intestine of wild-type mice and to promote tumor progression in the intestine of the APCmin/+ mice, indicating that PKCα plays a significant role in maintaining the intestinal epithelium homeostasis." (PMID 31109112, 2019). "Protein kinase C alpha is specifically linked to activation of PLD1 and PLD2; results show that a PKCα link to PLD is active in cell lines derived from both normal and tumourigenic epithelia, including P4E6 cells derived from an early tumour." (PMID 21266973, 2011). "However, no LOH in the 17q24.2 locus, nor other consistent mutations, deletions, amplifications associated with PRKCA and no mutations in other oncogenes or tumour suppressors were reported for these tumours." (PMID 41187221, 2025). "PRKCA participates in processes intricately linked to tumor-promoting events, and in PC-3 and DU-145 cell lines exhibits upregulation, whereas, in LNCaP cells, the apoptotic response induced by Phorbol 12-myristate 13-acetate (PMA) is promoted by NF-kB and active PRKCA mutants." (PMID 40481981, 2025). "Additionally, gene expression analysis showed autophagy to be one of the major pathways induced by hypoxia in colon CSCs; PRKCA/PKCα was shown to be involved in hypoxia-induced autophagy-mediated CSC self-renewal whereby knockdown of ATG5 significantly reduced in vivo tumour formation." (PMID 33799834, 2021). "Examination of the Mondor dataset showed that transcription of PRKCA and PRKCD were significantly upregulated in CRPC compared to HNPC tumours." (PMID 36550208, 2023). "The heatmap showed that more than half of the genes were downregulated in tumor tissue, and consistent with the univariate Cox regression analysis, they represented a better prognosis, including PTGS2, ACO1, DPP4, CRYAB, PRKCA, ACSL4 and AKR1C3." (PMID 34475496, 2021). "Matched to other genes, PRKCA, PRKCB, and PRKCE were more involved in many normal tissue mRNA profiles than tumor ones." (PMID 35174160, 2021). "Relative expression of PRKCA, FOXC2, and CTNND1 in all tumor samples, using the AgilentG4502A_07_3 array platform, were computed and visualized by a heat map." (PMID 29216867, 2017). "Furthermore, an important kinase, PRKCA/PKCα, that regulates hypoxia-mediated autophagy via ATG5 and Beclin1, stimulates tumor-initiating cell renewal in CRC." (PMID 36160153, 2022). "As a result, we found that ITPR1, ITPR2, and ITPR3 proteins may interact with tumor-promoting genes, such as PLCB1, PLCB2, PRKCA, and RGS21, which may partially explain its oncogene roles." (PMID 35580861, 2022). "Our data suggest that REST elevation in tumor cells may promote VM by driving VEGFR1 expression and possibly activating the protein kinase C alpha pathway." (PMID 33469989, 2021). "Some of these proteins were tumor suppressors, including Rb, FOXO3, and p27, and many proteins were kinases and involved in the regulation of cell proliferation, differentiation, and apoptosis, such as c-KIT, AKT, EGFR, MAPK1/3, PRKCA, SRC, ACVRL1, and JNK2." (PMID 32917965, 2020). "The result showed that five genes (PRKCA, ADORA1, PPARGC1A, KL, GNG7) could be identified as potentially prognostic factors, and they have also been suggested as tumor suppressor genes." (PMID 31661791, 2019). "In as much as peritumor tissue-derived CSC presented greater chemoresistance to treatments respect to core tumor derived-CSC, we decided to investigate by RT-qPCR the expression of the main modulators of EMT and/or drug resistance such as TWIST, EDN1 and PRKCA in several samples of GBM CSC." (PMID 27344175, 2016).
tumor (continued). "This revealed that tumor cells in MBMs not only exhibited significantly upregulated tumorigenesis and maintenance genes (e.g., MET and TBX2), but also expressed neural differentiation markers (e.g., NRG3, NELL1, NCAM1, ADNP) and cell adhesion molecules (e.g., CDH1, PRKCA)." (PMID 41284647, 2025). "First, these variants may have a protective effect against BC oncogenesis via the modulation of PRKCA expression, thus delaying if not stopping tumor development and growth." (PMID 35589867, 2022). "Thus, the genetic evidence indicates that PRKCA is likely to function as an oncogene, rather than a tumor suppressor gene, in chordoid gliomas." (PMID 29476136, 2018). "Conversely, to our knowledge, PRKCA cDNA was knocked-in only in the epidermis of transgenic mice where PKCα overexpression did not have any significant effect, except upon PMA induction of its activity that resulted in a striking inflammatory response, without tumor promotion." (PMID 31109112, 2019).
infection (31 papers, 2009 to 2025). The state of being infected such as from the introduction of a foreign agent such as serum, vaccine, antigenic substance or organism. "A similar mechanism was described in mice, where a phospholipase C (PLC)–PKD axis and protein kinase C-alpha (PKC-α) activity along with TFEB activation in murine macrophages are required after pathogenic infection, suggesting that this response is evolutionarily conserved." (PMID 33490073, 2020). "Upon LPS stimulation, EGCG treatment and Lv-PRKCA infection significantly increased PRKCA mRNA expression and protein levels, and EGCG treatment also relieved the effect of PRKCA silencing on PRKCA mRNA expression and protein levels." (PMID 34040072, 2021). "Single EGCG treatment or Lv-PRKCA infection relieved LPS-induced increases in MAPK signaling pathway-related proteins, while overexpression of PRKCA further promoted LPS-induced increases in these proteins." (PMID 34040072, 2021). "Single EGCG treatment or Lv-PRKCA infection attenuated LPS-induced increases in inflammatory factors; PRKCA silencing could reverse the suppressive effects of EGCG upon LPS-stimulated inflammatory factor release." (PMID 34040072, 2021). "This link between PRKCA and Th17 may be critical to gut infections and, specifically, to infection of Cryptosporidium in the developing infant gut." (PMID 32019797, 2020). "Suppression of PRKCA might play a role in the infection response, which is similarly reported in Brucella and some other intracellular pathogens, such as Salmonella, Leishmania, and Legionella infected macrophages." (PMID 29849669, 2018). "Under LPS stimulation, when compared with LPS group, EGCG or Lv-PRKCA infection restored, while Lv-shPRKCA further decreased PRKCA protein level; the effects of EGCG on PRKCA protein level were reversed by Lv-shPRKCA infection." (PMID 34040072, 2021). "Upon initial infection with RSV, PRKCA is activated and co-localizes with the virus." (PMID 34409086, 2021). "Upon LPS stimulation, EGCG treatment and Lv-PRKCA infection notably increased PRKCA expression level; knockdown of PRKCA further inhibited PRKCA expression level; and EGCG treatment reversed the inhibitory effect of PRKCA silencing on PRKCA expression level (P < 0.05)." (PMID 34040072, 2021).
cardiovascular disease (5 papers, 2014 to 2023). "PRKCA is expressed in all human tissues, and it has been shown that PRKCA is associated with cardiovascular disease, body weight, and bone structure." (PMID 37762538, 2023).
inflammation (4 papers, 2017 to 2023). Aberrant reaction of the microcirculation characterized by movement of fluid and leukocytes from the blood into extravascular tissues. "The findings generated from this study have demonstrated that PLCE1 and PRKCA are well correlated in the development of esophageal inflammation and its malignant transformation, their correlation has critical clinical significance." (PMID 28402280, 2017).
mental illnesses (2 papers, 2023 to 2024). "We identified dysregulations in four PKC genes—PRKCA, PRKCB, PRKCH, and PRKCI—known for their roles in mood regulation and stress response, crucial for neurodevelopment and linked to psychiatric disorders." (PMID 39238930, 2024).
neurodevelopmental disorder (2 papers, 2018 to 2019). A behavioral and cognitive disorder with onset during the developmental period that involves impaired or aberrant development of intellectual, motor, or social functions. "A meta-analysis performed on the de novo mutation data of 10,927 individuals with neurodevelopmental disorders found an excess of missense variants in the PRKCA gene." (PMID 31323926, 2019).
PRKCA also shares sentences with these, for which no sentence is quoted: Hyperglycemia (25 papers); diabetic nephropathy (19); bladder cancer (13); colorectal cancer (12); dilated cardiomyopathy (10); renal fibrosis (8); bacterial infection (6); endothelial dysfunction (6); ischemia (6); psoriasis (6); adenocarcinoma (5); cardiomyopathy (5); myocardial infarction (5); osteosarcoma (5); retinal degeneration (5); glaucoma (4); kidney disease (4); neurological disease (4); B-cell chronic lymphocytic leukemia (3); basal cell carcinoma (3); cardiac disease (3); cholestasis (3); COVID-19 (3); ganglioglioma (3); head and neck cancer (3); hypertrophy (3); lung (3); lung squamous cell carcinoma (3); membranous glomerulonephritis (3); metastatic melanoma (3).
A further 174 diseases each share a sentence with PRKCA in 3 papers or fewer.